CKM (creatine kinase, M-type)
Description:
Reversibly catalyzes the transfer of phosphate between ATP and various phosphogens (e.g. creatine phosphate). Creatine kinase isoenzymes play a central role in energy transduction in tissues with large, fluctuating energy demands, such as skeletal muscle, heart, brain and spermatozoa.
Synonyms: CPK-M; CKMM; M-CK
Tractability: Small molecule: it has a binding pocket of medium quality.
Target class: Enzyme; Transferase
Gene: Protein-coding gene on chromosome 19 (45,306,411 to 45,323,372, reverse strand). Ensembl gene ENSG00000104879.
Subcellular location: Cytoplasm
Pathways (Reactome):
Metabolism: Creatine metabolism
Gene Ontology:
Molecular function: protein binding; creatine kinase activity; catalytic activity; kinase activity; phosphotransferase activity, nitrogenous group as acceptor; transferase activity, transferring phosphorus-containing groups
Biological process: phosphocreatine biosynthetic process
Cellular component: cytosol; cytoplasm; extracellular region
Genetic constraint (gnomAD): Loss-of-function variants: 28 observed, 35.27 expected, observed/expected ratio (o/e) 0.79, 90% interval 0.59 to 1.09. The upper end of that interval is the gene's LOEUF score, 1.09, which puts it in group 4 of 6, group 1 being the genes least tolerant of losing a copy. Missense variants: 472 observed, 509.67 expected, observed/expected ratio (o/e) 0.93, 90% interval 0.86 to 1. Synonymous variants: 212 observed, 204.86 expected, observed/expected ratio (o/e) 1.03, 90% interval 0.92 to 1.16.
Homologues: Orthologues: chimpanzee CKM (100% identical), macaque CKM (99% identical), guinea pig CKM (97% identical), pig CKM (97% identical), mouse Ckm (97% identical), rat Ckm (96% identical), dog CKM (95% identical), rabbit CKM (89% identical), zebrafish ckma (88% identical), tropical clawed frog ckm (88% identical), zebrafish ckmb (85% identical), Drosophila melanogaster Argk1 (40% identical), and 8 more. Paralogues in human: CKB (81% identical), CKMT1A (65% identical), CKMT1B (65% identical), CKMT2 (62% identical).
Diseases named in the same sentence as CKM in open-access papers:
CKM is named in the same sentence as 71 diseases in open-access papers, as found by Europe PMC text mining. Sharing a sentence is not in itself a finding about the gene and the disease. The quoted sentences say what the papers report.
muscular dystrophy (12 papers, 2016 to 2025). Muscular dystrophy (MD) refers to a group of more than 30 genetic diseases characterized by progressive weakness and degeneration of the skeletal muscles that control movement. "FABP3 and CKM are secreted by muscle fibers into the blood upon muscle damage, particularly in cases of muscular dystrophy." (PMID 41104521, 2025).
myocardial infarction (11 papers, 2014 to 2025). Gross necrosis of the myocardium, as a result of interruption of the blood supply to the area, as in coronary thrombosis. "CKM, a cytosolic enzyme primarily found in cardiac muscle, is released into the bloodstream following myocardial injury, serving as a biomarker for myocardial infarction." (PMID 39513871, 2024). "Inhibition of CKM, a cytoplasmic enzyme, which is a serum marker for myocardial infarction and contributes to energy homeostasis, has been also reported to inhibit cardiac contractility and contractility of muscle." (PMID 31948008, 2020). "CKM is a creatine kinase involved in energy transduction, and is also an important serum marker for myocardial infarction." (PMID 26109061, 2015). "Furthermore, in clinical practices, markers such as cTnI, Myoglobin (MB), and Creatine kinase M (CKM) are quantified in blood to diagnose myocardial infarction resulting from IR injury." (PMID 38693114, 2024). "CKM is involved in enzyme homeostasis and is an important serum marker for myocardial infarction." (PMID 26269723, 2014). "The troponin genes (TNNC1, TNNT2, TNNI3), the creatine kinase gene (CKM), and the brain natriuretic peptide gene (NPPA) are recognized biomarkers of myocardial infarction." (PMID 40433126, 2025). "Notably, JUP and VDAC3 exhibited a high correlation with myocardial infarction biomarkers; however, JUP also demonstrated a significant correlation with TNNC1, TNNT2, TNNI, CKM, and NPPA (P < 0.05)." (PMID 40433126, 2025).
heart failure (7 papers, 2013 to 2025). Inability of the heart to pump blood at an adequate rate to meet tissue metabolic requirements. "In heart failure, acetylation may lead to a decrease in CKM activity, thereby exacerbating high-energy phosphorylation." (PMID 40463716, 2025). "A decrease in CKM activity due to acetylation may exacerbate high-energy phosphoryl transfer in the context of heart failure." (PMID 38918720, 2024).
Insulin resistance (6 papers, 2012 to 2025). Increased resistance towards insulin, that is, diminished effectiveness of insulin in reducing blood glucose levels. "In contrast, in utero exposure to synthetic glucocorticoids has been shown to induce a broad constellation of CKM-related conditions, including obesity, insulin resistance, hypertension, and kidney disease in adult offspring." (PMID 41008969, 2025). "Given that both EDC exposure and H2S deficiency are associated with obesity, insulin resistance, hypertension, and kidney disease, H2S likely represents a convergent mechanism underlying EDC-induced CKM programming." (PMID 41008969, 2025).
Obesity (5 papers, 2012 to 2025). Accumulation of substantial excess body fat. "We find UHRF1BP1 and ILRUN mediate the effect of obesity on CAD whereas methylation sites within NOS3 and CKM mediate the effect of their associated-risk factors on CAD." (PMID 33574266, 2021). "The interplay between gut microbiota, obesity, and CKM still warrants further investigation." (PMID 40927048, 2025). "Therefore, the interplay between gut microbiota, obesity, and CKM still warrants further investigation." (PMID 40927048, 2025).
Cachexia (3 papers, 2011 to 2022). Severe weight loss, wasting of muscle, loss of appetite, and general debility related to a chronic disease. "The qPCR results showed that, in comparison to the NC group, the expression level of CKM mRNA was significantly increased in the skeletal muscle of mice in the cachexia group and decreased following creatine supplementation." (PMID 36569317, 2022).
cardiac hypertrophy (3 papers, 2011 to 2025). "Animals genetically deficient in CKM develop myocardial hypertrophy and left ventricular dilation, as well as higher susceptibility to mitochondrial damage and cardiac disturbances in calcium homeostasis after ischemia and reperfusion." (PMID 21738806, 2011).
COVID-19 (3 papers, 2022 to 2024). A disease caused by infection with severe acute respiratory syndrome coronavirus 2. "Among them, CKMT2 and CKM stood out, and CKM increased for up to 60 days after the COVID-19 diagnosis." (PMID 35455962, 2022). "The overexpression of CKM and CKMT2 in the s-WAT of infected patients was transient, declining two months after COVID-19 diagnosis and correlating with the final recovery after surgical interventions." (PMID 35455962, 2022). "Furthermore, CKM presented several PTMs, such as phosphorylation of Lys-156 and Ser-158, which were only found in patients with SCI and COVID-19." (PMID 35455962, 2022).
dilated cardiomyopathy (3 papers, 2011 to 2022). Cardiomyopathy which is characterized by dilation and contractile dysfunction of the left and right ventricles. "In this paper, we observed a reduced expression of CKM, a key enzyme in myocardial energetic metabolism, in several dilated cardiomyopathies." (PMID 21738806, 2011).
hypertrophic cardiomyopathy (3 papers, 2022 to 2023). A condition in which the myocardium is hypertrophied without an obvious cause. "The myocyte-specific loss of Ndufs4 (driven by CKM-NLS-Cre) displayed features of hypertrophic cardiomyopathy." (PMID 37237867, 2023).
cardiomyopathy (2 papers, 2011 to 2023). A disease of the heart muscle or myocardium proper. "The reduced myocardial protein expression of CKM, observed in all cardiomyopathy groups, was reflected in the reduced total creatine kinase activity." (PMID 21738806, 2011). "Of note, in the comparison between cardiomyopathy groups, the average CKM expression was most decreased among CCC patients (13 % and 12 % reduction when compared to IDC and IC, respectively), although the difference was not statistically significant." (PMID 21738806, 2011). "Protein levels of CKM and CK activity were reduced in all three cardiomyopathy groups." (PMID 21738806, 2011). "The reduced protein expression of CKM was probably due to transcriptional regulation at least in the cases of CCC and IDC, since CKM mRNA expression was also significantly reduced in samples from patients of such groups, when compared to samples from individuals without cardiomyopathy." (PMID 21738806, 2011). "We found that mRNA expression of CKM was decreased in samples from patients with CCC and IDC when compared to samples from subjects without cardiomyopathy [78 % (p<0.05) and 69 % (p<0.05)]." (PMID 21738806, 2011).
Hypertension (2 papers, 2024 to 2025). The presence of chronic increased pressure in the systemic arterial system. "In addition, prenatal exposure to nicotine results in hypertension, hyperlipidemia, steatosis, and kidney disease, all of which are traits associated with CKM in adult offspring." (PMID 38542273, 2024). "The predominant protective effects of a variety of RAS-targeted interventions against CKM traits primarily encompass hypertension, succeeded by concerns such as kidney disease and CVD." (PMID 38542273, 2024). "Although GYY4137 has demonstrated protective effects against hypertension in models involving CSE inhibition and L-NAME-treated SHRs, its role has not yet been evaluated in models of CKM programming." (PMID 41008969, 2025).
melanoma (2 papers, 2025). A malignant, usually aggressive tumor composed of atypical, neoplastic melanocytes. "Recently, we searched for target proteins of 16:0/16:0-PA in myoblasts and melanoma cells, and identified CKM and heat shock protein 27 (HSP27) as 16:0/16:0-PA-binding proteins." (PMID 41080753, 2025). "We previously identified CKM and HSP27 as the target proteins of 16:0/16:0-PA in C2C12 myoblasts and AKI melanoma cells, respectively." (PMID 41080753, 2025).
sarcoma (2 papers, 2015 to 2019). A usually aggressive malignant neoplasm of the soft tissue or bone. "Survival analysis of the top ten hub DEGs indicate that overexpression of AC104831.1, CKM, and NEB was significantly associated with poor OS in patients with sarcoma." (PMID 31598169, 2019).
Stroke (2 papers, 2024 to 2025). Sudden impairment of blood flow to a part of the brain due to occlusion or rupture of an artery to the brain. "The association between CumAIP and stroke was further stratified by CKM stage." (PMID 40988399, 2025). "The incidence of incident stroke demonstrated a clear stage‐dependent trend with advancing CKM." (PMID 40988399, 2025).
adenomyosis (1 paper, 2021). The growth of endometrial tissue inside the muscular wall of the uterine corpus. "The expression levels of ITGA1, ITGB1, LAMC1, and CKM are downregulated in the adenomyosis group compared with those in control group, while those proteins are successfully recovered by anti-NGF treatment." (PMID 32676925, 2021). "In addition, the level of CKM was decreased in adenomyosis group whereas increased in anti-NGF group." (PMID 32676925, 2021). "In addition, the level of CKM was decreased in adenomyosis group, while that was increased in anti-NGF group." (PMID 32676925, 2021). "Western blotting confirmed that the expression levels of integrin alpha-1 (ITGA1), integrin beta-1 (ITGB1), laminin subunit gamma-1 (LAMC1), and creatine kinase M-type (CKM) were decreased in adenomyosis group, whereas those levels were elevated after anti-NGF treatment." (PMID 32676925, 2021). "In the current study, we noted a crucial role of CKM during onset and recovery of adenomyosis, which indicated that anti-NGF treatment could improve the energy metabolism of uterine adenomyosis in mice." (PMID 32676925, 2021). "Furthermore, ITGB1, ITGA1, LAMC1, and CKM might participate in the recovery of adenomyosis." (PMID 32676925, 2021).
depression (1 paper, 2025). "Although antioxidant-rich diets have been linked separately to CKM components and to depressive symptoms, the joint phenotype (CKM with depression) and its relation to mortality remain understudied." (PMID 41310757, 2025). "In this observational NHANES analysis (2007–2010), CKM–depression comorbidity was the primary outcome, and all-cause mortality was the secondary outcome." (PMID 41310757, 2025). "Further regression results demonstrated that intake of these flavonoid subclasses negatively correlates with CKM–depression comorbidity and reduces all-cause mortality risk." (PMID 41310757, 2025). "Through feature selection processes, LASSO regression identified 21 candidate biomarkers linked to CKM–depression comorbidity, while the Boruta algorithm prioritized 54 variables." (PMID 41310757, 2025). "Specific anthocyanidins were cross-sectionally associated with lower CKM–depression comorbidity and, for petunidin and total anthocyanidins, with lower mortality hazard." (PMID 41310757, 2025). "LGBM provided the best discrimination for CKM–depression comorbidity and consistently highlighted albumin and family PIR as dominant predictors, with anthocyanidins contributing additional but smaller predictive information (as confirmed by NRI and IDI)." (PMID 41310757, 2025). "Biologically, CKM and depression share inflammation and oxidative/REDOX stress pathways (together with neuroendocrine and autonomic dysregulation)." (PMID 41310757, 2025). "Future work should include external validation, prospective and interventional studies, and mechanistic investigations (inflammation, redox, lipid pathways, and socioeconomic context) to clarify whether and to what extent modifying anthocyanidin intake can influence CKM–depression outcomes." (PMID 41310757, 2025).
lung squamous cell carcinoma (1 paper, 2025). "Three compounds (gallic acid, betulinic acid, and caffeic acid) had a significant inhibitory effect on lung squamous cell carcinoma via five biolabels (CPS1, CKM, CPT1B, COX5B, and COX4I1)." (PMID 41502520, 2025).
malaria (1 paper, 2018). Malaria is a serious and sometimes fatal disease caused by a parasite that commonly infects a certain type of mosquito which feeds on humans. "Four proteins (CA2, CKB, CKM, DAPK1) were only found to be associated with severe compared to mild malaria." (PMID 30442134, 2018).
malignant glioma (1 paper, 2015). A grade III or grade IV glioma arising from the central nervous system. "Although human CKM (NM_001824) is found in molecularly abnormal malignant gliomas, Ckm and RGD1561759 have rarely been discussed in the context of neuronal disorders." (PMID 26580597, 2015).
osteosarcoma (1 paper, 2023). A usually aggressive malignant bone-forming mesenchymal neoplasm, predominantly affecting adolescents and young adults. "We designed a system to achieve specific expression of CRISPR-dCas9-KRAB in osteosarcoma cells by using the creatine kinase muscle (CKM) promoter to drive dCas9-KRAB and the telomerase reverse transcriptase (TERT) promoter to drive single guide (sg)RNA expression." (PMID 37415116, 2023).
prion disease (1 paper, 2023). A transmissible disease that is caused by a protein that is able to induce abnormal folding of normal cellular proteins, leading to characteristic spongiform brain changes, which are associated with neuronal loss without an inflammatory response. "Other noteworthy hub-hub genes, including CKM, RYR1, and VWF, presented lower expression in LDM tissue and have critical roles in metabolic pathways, oxytocin signaling pathway, ECM-receptor interaction, prion disease, and calcium signaling pathway." (PMID 37627391, 2023).
tumor (8 papers, 2012 to 2025). "Similar to MYH2, CKM (Muscle type of CK) is down-regulated in tumor (GATA3 mutant and non-mutant) tissues." (PMID 33462316, 2021).
cancer (5 papers, 2012 to 2025). A tumor composed of atypical neoplastic, often pleomorphic cells that invade other tissues. "However, there is still a lack of research on the role of CKM in cancer biology." (PMID 35844514, 2022).
infection (5 papers, 2013 to 2024). The state of being infected such as from the introduction of a foreign agent such as serum, vaccine, antigenic substance or organism. "Altogether, our data suggest that the presence of CKMT2 or CKM in the s-WAT of SCI/PU post-COVID patients within six weeks after infection may represent a prognostic biomarker of poor postsurgical recovery." (PMID 35455962, 2022).
heart diseases (1 paper, 2025). "For premature mortality from heart diseases, the adjusted HRs (95% CI) for CKM stages 1–4 were 0.99 (0.40–2.47), 1.76 (0.70–4.40), 4.43 (1.61–12.18), and 7.40 (3.40–16.13), respectively." (PMID 39952015, 2025).
Neurological disorders (1 paper, 2025). "Neurological disorders have been associated with mutations in CKM genes including MED13L syndrome." (PMID 40919805, 2025).
CKM also shares sentences with these, for which no sentence is quoted: rhabdomyolysis (4 papers); kidney disease (2); myopathies (2); myositis (2); polymyositis (2); AIDS (1); Alagille syndrome (1); Alzheimer disease (1); angina pectoris (1); Aortic dissection (1); atrial fibrillation (1); Barth syndrome (1); brain diseases (1); cardiac arrhythmia (1); chronic heart failure (1); Cirrhosis (1); cognitive decline (1); colitis (1); colon cancer (1); colorectal cancer (1); coronary artery disease (1); dermatomyositis (1); diabetes (1); Duchenne muscular dystrophy (1); hyperandrogenism (1); Hyperinsulinemia (1); hypophosphatasia (1); intrahepatic cholangiocarcinoma (1); left ventricular dilation (1); left ventricular hypertrophy (1).
A further 14 diseases each share a sentence with CKM in 1 paper.